SNORA84 (small nucleolar RNA, H/ACA box 84)
Gene: Small nucleolar RNA gene on chromosome 9 (92,292,461 to 92,292,593, reverse strand). Ensembl gene ENSG00000239183.
Gene Ontology:
Biological process: RNA processing
Cellular component: nucleolus
Homologues: Orthologues: chimpanzee SNORA84 (99% identical), macaque SNORA84 (96% identical), dog SNORA84 (89% identical), rabbit SNORA84 (89% identical), pig SNORA84 (88% identical), mouse Gm25394 (85% identical), mouse Gm25989 (85% identical), rat LOC120098012 (85% identical), mouse Gm23513 (84% identical), rat Snora84 (80% identical).